STAT3 (signal transducer and activator of transcription 3)
Diseases named in the same sentence as STAT3 in open-access papers (continued):
Sharing a sentence is not in itself a finding about the gene and the disease.
emphysema (8 papers, 2013 to 2025). "Concerning pulmonary inflammation, it was observed that IL-6 directly activates STAT3, while in pulmonary emphysema, IL-6 drives the activation of STAT3 in a different manner." (PMID 29326759, 2017). "Firstly, they propose that sIL-6R acts via STAT3 activation to initiate lung inflammation and, secondly, through a pathway whereby sIL-6R activates mTORC1 and contributes to the development of emphysema." (PMID 28334838, 2017). "Apoptosis is a critical process in the development of emphysema and STAT3 regulates apoptotic responses in vivo." (PMID 24101903, 2013). "Therefore, the present study investigated the effects of AE on pulmonary inflammation and emphysema, on systemic inflammation, and on STAT3 signaling in a smoke model of COPD in mice." (PMID 29326759, 2017). "Furthermore, we ascertained that inhibition of STAT3 activation partially ameliorated the Al2O3 NPs-induced emphysema and airway remodeling in murine lungs." (PMID 29233151, 2017). "Our findings suggest that direct targeting of Siglec-F+ neutrophils with a depleting antibody or G-CSF signaling inhibitor other than a STAT3 inhibitor for blocking the development of Siglec-F+ neutrophils could be a potential therapeutic approach for emphysema." (PMID 40461699, 2025). "In alignment with these observations, our findings identified an upregulation of RAGE and STAT1 genes in lung tissue, alongside increased expression levels of RAGE, p-JAK2, p-STAT1, p-STAT3 and p-STAT5 in pulmonary mDCs in a smoking-induced mouse model of emphysema." (PMID 40951546, 2025). "We hypothesize that as a consequence of suppressed expression of PTPN6, STAT3 activation and PDCD4 expression increase in airway and alveolar epithelial cells, leading to apoptosis, inflammation and emphysema in experimental COPD." (PMID 29233151, 2017). "The fact that STAT3 negatively regulated MMP-12 is significant as this protease is upregulated in COPD patients and plays a critical role in smoke-induced emphysema in mice." (PMID 24101903, 2013). "administration of AG490 (JAK2 inhibitor) or HJC0152 (STAT3 inhibitor) significantly reduced both the frequency and absolute cell number of Siglec-F+ neutrophils in the lungs of PPE-treated mice, and this reduction was accompanied by marked alleviation of emphysema symptoms, as assessed by MLI." (PMID 40461699, 2025). "Paradoxically, miR-let-7c inhibits M2 macrophage polarization through the IL-6/STAT3 pathway, suggesting that excessive M2 polarization may contribute to emphysema rather than repair in COPD." (PMID 41229413, 2025).
erythroleukemia (8 papers, 2018 to 2025). Acute erythroid leukemia characterised by the presence of at least 50% erythroid precursors and at least 20% myeloblasts in the bone marrow. "These beneficial effects can be explained by the BW18-mediated inactivation of PDGFRB and JAK2/STAT3 pathway in erythroleukemia cells." (PMID 38794198, 2024). "Previous studies have shown that the activation of Stat3 could inhibit erythroid differentiation through the up-regulation of Pu.1, thus exacerbating the development of erythroleukemia." (PMID 38794198, 2024). "In addition, the anti-erythroleukemia effect of H-120 may be related to the inhibition of the activation of STAT3/c-Myc signal pathway." (PMID 38611876, 2024). "In summary, N2 represents a potent differentiation therapy candidate for erythroleukemia, uniquely targeting JAK2 and activating downstream JAK2/STAT3, JAK2/PKCδ/STAT3 and JAK2/PKCδ/MAPK pathways to facilitate megakaryocytic differentiation." (PMID 39791711, 2024).
glomerulonephritis (8 papers, 2009 to 2022). A renal disorder characterized by damage in the glomeruli. "Previous study has reported that the activation of STAT3 signaling pathway is an important factor to induce the progression of glomerulonephritis." (PMID 36575400, 2022). "Increased STAT3 expression in kidneys has been detected during severe oxidative stress and glomerulonephritis." (PMID 19416544, 2009). "We found aberrant activation of EGFR and STAT3 in podocytes of the experimental glomerulonephritis model, as shown by the striking staining of phosphorylated EGFR and STAT3, which were not present in healthy controls and eliminated in the NTS rats with MP treatment." (PMID 35223886, 2022). "Thus, the activation of the STAT3 signaling pathway enhances the progression of glomerulus sclerosis in glomerulonephritis." (PMID 36575400, 2022). "The effects of Tregs may be context dependent, with evidence for roles for immunoregulatory roles both for endogenous Tbet‐expressing Tregs and STAT‐3‐expressing Tregs in experimental glomerulonephritis." (PMID 29484182, 2018). "Since podocyte EGFR/STAT3 signaling is known to mediate the development of anti-GBM glomerulonephritis, we investigated the effect of glucocorticoids on EGFR/STAT3 signaling in podocytes." (PMID 35223886, 2022). "In another study, deletion of signal transducer and activator of transcription 3 (STAT3) a downstream target of activated EGFR, in podocytes was found to markedly reduce crescent formation in the mouse model of anti-GBM glomerulonephritis." (PMID 35223886, 2022). "In a rat model of anti-GBM glomerulonephritis, glucocorticoids treatment significantly attenuated the proteinuria, crescent formation, parietal epithelial cell (PEC) activation and proliferation, accompanied by elimination of podocyte EGFR/STAT3 signaling activation." (PMID 35223886, 2022).
Hashimoto thyroiditis (8 papers, 2012 to 2025). An autoimmune disorder caused by the production of autoantibodies against thyroid tissue. "For example, STAT3 rs3816769 and rs744166 polymorphisms were shown to play a significant role in susceptibility to autoimmune thyroid disease Hashimoto’s thyroiditis and Graves’ disease in the Polish population." (PMID 29609539, 2018). "A central finding in our study cohort of patients with lymphocytic thyroiditis was that an increase in stromal fibrosis was associated with reduced levels of STAT3 activation." (PMID 22527947, 2012). "In five out of ten patients with chronic lymphocytic thyroiditis, we found intrathyroidal expression of STAT3, which was predominately located in regions with almost complete destruction of the follicular architecture." (PMID 22527947, 2012). "Activated STAT3 amplifies the expression of inflammatory cytokines and S1PR1, which further exacerbates the development of Hashimoto thyroiditis." (PMID 37858140, 2023). "In Hashimoto’s thyroiditis, T CD4+ lymphocytes, under the action of antigen presenting cells (APCs), activate RORγt through the JAK2/STAT3 pathway and differentiate into Th17 cells." (PMID 36339447, 2022).
hypertriglyceridemia (8 papers, 2011 to 2025). A laboratory test result indicating elevated triglyceride concentration in the blood. "Adipose IL-10 and STAT3 mRNA expression and serum IL-10 reduced in obese children with hypertriglyceridemia and in HFD obese rats." (PMID 29895283, 2018). "Present study has shown that adipose STAT3 expression was decreased in obese children with hypertriglyceridemia and in HFD obese rats." (PMID 29895283, 2018). "Overexpression of STC2 significantly attenuated fatty liver and hypertriglyceridemia in obese mice through activation of the STAT3 signaling pathway." (PMID 30038584, 2018). "STC2 ameliorated hepatosteatosis and hypertriglyceridemia in obese mice, mainly through activation of the STAT3 signaling pathway." (PMID 30038584, 2018). "QRT-PCR showed that when compared with the non-obese and the obese without hypertriglyceridemia group, STAT3 mRNA expression were lower in obese children with hypertriglyceridemia." (PMID 29895283, 2018). "Investigating the involvement of IL-6 and IL-10 in the activation of STAT3 and NF-κB pathways and in the regulation of endocytosis via GSK3β inhibition or actin filament rearrangements could provide a deeper understanding of the increased BBB permeability seen in hypertriglyceridemia." (PMID 36882782, 2023).
inflammatory skin disease (8 papers, 2012 to 2025). Inflammatory skin disorders covers a broad category that includes many conditions ranging in severity, from mild itching to grave medical health complications These disorders are common in people of all ages and races. "Meanwhile, the Janus kinase/signal transducer and activator of transcription (JAK/STAT) signaling pathway, particularly the JAK1/STAT3 axis, has been implicated in both immune activation and vascular regulation in inflammatory skin diseases." (PMID 40725084, 2025). "STAT3, in particular, is activated downstream of multiple pro-inflammatory and Th2-associated cytokines and has been implicated in a wide range of inflammatory skin diseases and tumors." (PMID 40725084, 2025). "The noted attenuation of AKT and STAT3 phosphorylation by EHMF further underscores its promising role in mitigating other inflammatory skin disorders where these signaling pathways are implicated." (PMID 39469625, 2024). "Itch is an inflammatory skin disease, and recent research has demonstrated that astrocytes in dorsal horn of spine are triggered in contact dermatitis and AD models by regulating STAT3 activation, and contribute critically to itch." (PMID 40443235, 2025). "Furthermore, when this balance is broken and STAT3 activation is out of control, inflammatory skin disease is induced without any abnormalities in the immune cells." (PMID 22792286, 2012).
iron deficiency (8 papers, 2013 to 2026). "Experimental models have shown that iron deficiency can elevate pulmonary artery pressure, promote right ventricular hypertrophy and vascular remodeling, and upregulate HIF1α, HIF2α, and STAT3 signaling pathways — changes that are reversible with iron therapy." (PMID 41451092, 2025). "Additionally, hepcidin deficiency due to iron deficiency is associated with a promotion of IL13 secretion by macrophages via the STAT3 pathway in the heart." (PMID 39341502, 2024). "Conversely, insulin enhances hepcidin synthesis in liver cells by activating STAT3 via the JAK/STAT signaling pathway, potentially leading to iron deficiency." (PMID 41515226, 2025). "Iron deficiency-induced reduction in hepcidin promotes the expression of IL6 and STAT3." (PMID 39341502, 2024).
kidney injury (8 papers, 2015 to 2025). Trauma to the kidney. "In this study, we show that ACSL4 is overexpressed by tubular epithelium in a model of ER-stress-induced kidney injury and is upregulated in response to STAT3 signaling in a cell extrinsic manner." (PMID 38799564, 2024). "The data provide evidence for meprin β modulation of IL‐6/JAK2/STAT3 signaling and their convergence to activate the downstream target genes of IL‐6 signaling in IR‐induced kidney injury." (PMID 36117389, 2022). "In summary, our data suggest that proteolytic processing of IL‐6 by meprin β plays an important role in modulating IL‐6 expression and influences the downstream signal transduction/pathway mediated via JAK2/STAT3 in IR‐induced kidney injury." (PMID 36117389, 2022). "In conclusion, the study demonstrated that EA at BL23 exhibited anti‐HUA and nephroprotective effects by inhibiting both the NLRP3 inflammasome and the IL‐6/JAK/STAT3 signaling pathway, reducing renal inflammation and supporting its therapeutic potential for HUA‐associated kidney injury." (PMID 41278550, 2025). "Similarly, in a mouse model of obstructive kidney injury, STAT3 is activated and inhibition of STAT3 with the drug S3I-201 attenuates interstitial fibrosis and immune cell infiltration in the injured kidney." (PMID 26678048, 2015). "Overall, we identified BCR and STAT3 as key players in DDR1-mediated proinflammatory and profibrotic effects after kidney injury." (PMID 34941574, 2022). "Thus, DDR1 contributes to acute and chronic kidney injury by regulating BCR and STAT3 phosphorylation and in turn the production of MCP-1 and TGF-β." (PMID 34941574, 2022). "Since BRL52537, a kappa-opioid receptor agonist, could regulate p-STAT3 but not STAT3 expression in cerebral IRI and is involved in kidney injury, we used BRL52537 to assess whether p-STAT3 is necessary for the protective effects of BA." (PMID 34796171, 2021).
medullary thyroid carcinoma (8 papers, 2015 to 2025). "It has been reported that medullary thyroid cancer patients with RET germline mutations show higher STAT3 activation and its nuclear localization." (PMID 34207842, 2021). "Meanwhile, it has been reported that the JAK/STAT3 pathway is also activated in thyroid medullary carcinoma; consequently, it is only plausible that ATX expression is somehow associated with the JAK/STAT3 pathway." (PMID 31455351, 2019). "The possible mechanism for the high expression of ATX in thyroid medullary carcinoma is the JAK/STAT3 pathway." (PMID 31455351, 2019). "In other studies, CDK5 promoted medullary thyroid carcinoma cell growth by regulating STAT3 activation and cell proliferation." (PMID 29312535, 2017). "In addition to the activation of RET and STAT3, it has been noted that CDK5 regulates STAT3 in medullary thyroid cancer, influencing cell proliferation." (PMID 37046823, 2023). "Besides, our previous study demonstrated that CDK5 phosphorylates STAT3 in prostate and medullary thyroid cancer cells." (PMID 34207842, 2021). "STAT3 activation status showed similar activation status with CDK5, suggesting that STAT3 activation might be CDK5-dependent in GDNF-induced medullary thyroid cancer cell proliferation." (PMID 34207842, 2021). "Furthermore, our previous findings have demonstrated that CDK5 regulates STAT3 activation in the medullary thyroid cancer cell proliferation, and inhibition of STAT3 as well as CDK5 decelerates human medullary thyroid cancer cell proliferation." (PMID 34207842, 2021). "Since we have previously reported that CDK5 phosphorylates STAT3 at Ser727 site in prostate and medullary thyroid cancer cells, thus, we thought that STAT3 might be a potential downstream of CDK5 in GDNF-induced RET signaling in medullary thyroid cancer cell proliferation." (PMID 34207842, 2021). "The cancer stem cells in medullary thyroid carcinoma are characterized by chemo- and radio-resistance induced by increased signaling pathways, such as signal transducer and activator of transcription 3 (STAT3), c-Met, SOX2, rearranged during transfection (RET), CD44." (PMID 32244473, 2020). "Suppressing both STAT3 and CDK5 has been shown to slow down human medullary thyroid cancer cell proliferation." (PMID 37046823, 2023). "Correspondingly, in medullary thyroid cancer (MTC), through the Ser727 phosphorylation of STAT3, CDK5 modulates cell proliferation." (PMID 33396266, 2020). "Interestingly, a relationship between STAT3 activation and IFI16 expression during cell apoptosis was detected in medullary thyroid carcinoma and mammary epithelial cells." (PMID 26185770, 2015).
peripheral nerve injury (8 papers, 2013 to 2025). Injury to a peripheral nerve. "IL-6 is predominantly induced as challenged by PGE2 and TNF-α in peripheral nerve injury, and is implicated in neuropathic pain via MAPK and STAT3 signaling." (PMID 38419042, 2024). "Stat3 inhibitors are used to treat peripheral nerve injury-induced hyperexcitability within dorsal horn neurons, pain behaviors, chronic constriction injury, and signaling of IL-6 cytokines." (PMID 32038157, 2019). "In a recent study, an important role of the JAKS and STAT3 signaling pathways has been demonstrated in the proliferation of astrocytes in the dorsal horn of the spinal cord in a model of peripheral nerve injury in rats." (PMID 26222740, 2015). "Using gliotropic lentiviral vectors in a rat model of peripheral nerve injury, Jak-Stat3 pathway was inhibited by Socs3, in a negatively feedback fashion, resulting in a decrease in neuroinflammation and mechanical allodynia." (PMID 24098399, 2013). "Phosphorylation of STAT3 is a known consequence of peripheral nerve injury, and particularly noteworthy in the context of our study: several of the mediators we identified as up-regulated with nerve injury in mouse mural cells are cytokines which activate the JAK/STAT pathway (Il6, Lif and Clcf1)." (PMID 40381746, 2025). "Therefore, IL-6 released into the CSF can further activate STAT3, amplifying the inflammation responses and facilitating of the propagation of pain following peripheral nerve injury." (PMID 38419042, 2024). "A previous study reported that blocking of STAT3 signaling pathway could attenuate ipsilateral mechanical and thermal hypersensitivity and the mirror-image mechanical allodynia induced by peripheral nerve injury." (PMID 35144528, 2022).
peripheral T-cell lymphoma (8 papers, 2018 to 2024). "In peripheral T-cell lymphoma cell line Hut78, knocking down STAT3 reduced Bcl-XL expression and promoting apoptosis." (PMID 34736477, 2021). "In peripheral T-cell lymphoma (PTCL) and extranodal NKTCL, recurrent mutations in STAT3 are most frequent, followed by JAK1, JAK3, and SOCS1." (PMID 31861597, 2019). "STAT3 is mutated in 6% of natural killer/T-cell lymphomas (NKTCL) and 8% of peripheral T-cell lymphoma (PTCL)." (PMID 31861597, 2019). "Currently, various drugs that inhibit the activity of the JAK/STAT3 pathway or SETD2-targeted drugs are in the research and development stage or clinical trials, and some have been proven to have antitumor activity against various subtypes of peripheral T-cell lymphomas." (PMID 38520011, 2024).
scleroderma (8 papers, 2017 to 2022). Scleroderma is a rare autoimmune connective tissue disorder characterized by abnormal hardening of the skin and, sometimes, other organs. "STAT3 has recently been identified as a putative mediator of dermal fibrosis in patients with scleroderma and its murine models, acting downstream of TGF-β to drive pro-fibrotic fibroblast responses." (PMID 33897686, 2021). "Another STAT3 inhibitor S3I–201 not only impaired the progression of fibrosis in a bleomycin model of scleroderma but also appeared to induce regression of established fibrosis." (PMID 30081609, 2018). "Blocking the OSM/OSMRβ pathway or inhibiting the STAT3 pathway could serve as a potential therapy for patients with scleroderma." (PMID 32736577, 2020). "In the experimental scleroderma study, it has been shown that with TOFA treatment, there is a decrease in skin thickness, active STAT3 and collagen levels." (PMID 35169250, 2022). "If the approach of leveraging genetic data in evaluating therapies gains traction, the possible signal in CTD/scleroderma is potentially supported by existing meta-analyses data in scleroderma not stratified by presence of PAH, where STAT3 emerges as a risk loci." (PMID 34588193, 2022).
spinal cord injury (8 papers, 2013 to 2025). Penetrating and non-penetrating injuries to the spinal cord resulting from traumatic external forces (e.g., WOUNDS, GUNSHOT; WHIPLASH INJURIES; etc.). "Recently, it has been reported that STAT3 play a Critical role in the regulation of astrogliosis and scar formation in Spinal Cord Injury." (PMID 23383263, 2013). "Similarly, STAT3 may also be essential for glial scar formation and astrocytic neuroprotection after spinal cord injury (SCI) 13, 32, 38-40." (PMID 34345208, 2021). "In the spinal cord injury (SCI) model, IL-6-induced activation of the JAK2/STAT3 signaling pathway in spinal dorsal horn microglia and astrocytes contributes to the progression of pain." (PMID 40093024, 2025). "Indeed conditional ablation of SOCS3, but not STAT3, produces contraction of lesion area and notable improvement in functional recovery after spinal cord contusion." (PMID 25750613, 2015).